HSPD1 (heat shock protein family D (Hsp60) member 1)
Description:
Chaperonin implicated in mitochondrial protein import and macromolecular assembly. Together with Hsp10, facilitates the correct folding of imported proteins. May also prevent misfolding and promote the refolding and proper assembly of unfolded polypeptides generated under stress conditions in the mitochondrial matrix. The functional units of these chaperonins consist of heptameric rings of the large subunit Hsp60, which function as a back- to-back double ring. In a cyclic reaction, Hsp60 ring complexes bind one unfolded substrate protein per ring, followed by the binding of ATP and association with 2 heptameric rings of the co-chaperonin Hsp10. This leads to sequestration of the substrate protein in the inner cavity of Hsp60 where, for a certain period of time, it can fold undisturbed by other cell components. Synchronous hydrolysis of ATP in all Hsp60 subunits results in the dissociation of the chaperonin rings and the release of ADP and the folded substrate protein (Probable).
Synonyms: CPN60; HSP-60; Hsp60; GroEL; HLD4; HSP65; HuCHA60; SPG13
Tractability: Small molecule: a structure with a bound ligand is known; a high-quality ligand is known. Antibody: its Gene Ontology location is reachable by antibodies, with high confidence. PROTAC: UniProt records ubiquitination sites on it; ubiquitination databases record sites on it; its protein half-life has been measured; a small molecule that binds it is known.
Target class: Other cytosolic protein
Gene: Protein-coding gene on chromosome 2 (197,486,580 to 197,516,737, reverse strand). Ensembl gene ENSG00000144381.
Subcellular location: Mitochondrion matrix
Subcellular location (Human Protein Atlas): Mitochondria
Pathways (Reactome):
Cellular responses to stimuli: Mitochondrial unfolded protein response (UPRmt)
Gene expression (Transcription): TFAP2A acts as a transcriptional repressor during retinoic acid induced cell differentiation
Metabolism of proteins: Mitochondrial protein degradation
Protein localization: Mitochondrial protein import
Gene Ontology:
Molecular function: apolipoprotein A-I binding; apolipoprotein binding; cysteine-type endopeptidase activator activity; double-stranded RNA binding; enzyme binding; high-density lipoprotein particle binding; lipopolysaccharide binding; protein binding; protein-folding chaperone binding; RNA binding; ubiquitin protein ligase binding; ATP hydrolysis activity; DNA replication origin binding; single-stranded DNA binding; ATP binding; ATP-dependent protein folding chaperone
Biological process: adhesion of symbiont to host; B cell activation; B cell proliferation; biological process involved in interaction with symbiont; isotype switching to IgG isotypes; MyD88-dependent toll-like receptor signaling pathway; negative regulation of apoptotic process; negative regulation of execution phase of apoptosis; positive regulation of execution phase of apoptosis; positive regulation of interferon-alpha production; positive regulation of interleukin-10 production; positive regulation of interleukin-12 production; positive regulation of interleukin-6 production; positive regulation of macrophage activation; positive regulation of T cell activation; positive regulation of T cell mediated immune response to tumor cell; positive regulation of type II interferon production; protein refolding; protein stabilization; response to unfolded protein; T cell activation; 'de novo' protein folding; apoptotic mitochondrial changes; chaperone-mediated protein complex assembly; mitochondrial unfolded protein response; and 5 more
Cellular component: cell surface; clathrin-coated pit; coated vesicle; cytoplasm; cytosol; early endosome; extracellular exosome; extracellular region; lipopolysaccharide receptor complex; membrane; mitochondrial matrix; mitochondrion; plasma membrane; protein-containing complex; sperm midpiece; mitochondrial inner membrane; secretory granule; migrasome
Genetic constraint (gnomAD): Loss-of-function variants: 2 observed, 34.05 expected, observed/expected ratio (o/e) 0.0587, 90% interval 0.023 to 0.19. The upper end of that interval is the gene's LOEUF score, 0.19, which puts it in group 1 of 6, group 1 being the genes least tolerant of losing a copy. Missense variants: 336 observed, 516.98 expected, observed/expected ratio (o/e) 0.65, 90% interval 0.59 to 0.71. Synonymous variants: 164 observed, 173.89 expected, observed/expected ratio (o/e) 0.94, 90% interval 0.83 to 1.07.
Homologues: Orthologues: chimpanzee HSPD1 (99% identical), macaque HSPD1 (99% identical), rabbit HSPD1 (99% identical), mouse Hspd1 (98% identical), rat Hspd1 (98% identical), guinea pig HSPD1 (96% identical), rat Hspd1l1 (96% identical), tropical clawed frog hspd1 (89% identical), zebrafish hspd1 (87% identical), pig HSPD1 (82% identical), Drosophila melanogaster Hsp60A (74% identical), Drosophila melanogaster Hsp60C (72% identical), and 3 more. Paralogues in human: CCT6A (20% identical), CCT7 (20% identical), CCT2 (20% identical), CCT6B (20% identical), CCT3 (19% identical), TCP1 (19% identical), CCT8 (18% identical), PIKFYVE (17% identical), CCT5 (17% identical), CCT4 (16% identical), CCT8L2 (16% identical), MKKS (13% identical), and 1 more.
Diseases named in the same sentence as HSPD1 in open-access papers:
HSPD1 is named in the same sentence as 263 diseases in open-access papers, as found by Europe PMC text mining. Sharing a sentence is not in itself a finding about the gene and the disease. The quoted sentences say what the papers report.
atherosclerosis (50 papers, 2005 to 2026). A disease characterized by the build-up of fatty material and calcium deposition in the arterial wall resulting in partial or complete occlusion of the arterial lumen. "Strikingly, 10 genes exhibited shared dysregulation in both aging and atherosclerosis, including Vcam1, Apoe, Gdf15, Timp1, Cxcl12, Hspd1, Serpine1, App, Eln, and Hif1a, suggesting their potentially critical roles in the atherosclerosis driven by aging in HGPS mice." (PMID 41209003, 2025). "Moreover, HSPD1/HSP60 autoantibodies, isolated from patients with CVD, could promote atherosclerosis in ApoE−/− mice." (PMID 29240668, 2017).
diabetes (22 papers, 2008 to 2024). "Multivariate survival analysis of breast cancer associated with genetic variations of FTO, IL-6, HSPD1 genes and diabetes." (PMID 28591216, 2017). "We further analyzed the joint effects of FTO, IL-6, HSPD1 polymorphisms with diabetes on breast cancer risk." (PMID 28591216, 2017). "Joint effects between genetic variations of FTO, IL-6, HSPD1 genes and diabetes on breast cancer risk." (PMID 28591216, 2017). "Multivariate odds ratio of breast cancer risk associated with genetic variations of FTO, IL-6, HSPD1 genes and diabetes." (PMID 28591216, 2017). "Our results suggest that the contribution of diabetes to breast cancer risk might be modified by IL-6 rs1800796 and HSPD1 rs2605039." (PMID 28591216, 2017). "Diabetes and HSPD1 rs2605039 were also associated with breast cancer survival." (PMID 28591216, 2017). "In summary, our results suggested that diabetes was associated with breast cancer risk in the Chinese population, which may be modified by genetic variations of IL-6 rs1800796 and HSPD1 rs2605039." (PMID 28591216, 2017). "IL-6 rs1800796 and HSPD1 rs2605039 had interactions with diabetes on breast cancer risk." (PMID 28591216, 2017). "We evaluated the associations of diabetes, combined with the polymorphisms in the genes of fat mass and obesity-associated gene (FTO), interleukin 6 (IL-6), and heat shock protein 60 (HSPD1), with breast cancer risk and survival in a Chinese Han population." (PMID 28591216, 2017). "In the univariate model, diabetes, FTO rs3751812, and IL-6 rs1800796 were associated with neither OS nor PFS of breast cancer patients (all P values > 0.05), while HSPD1 rs2605039 was significantly associated with PFS (P = 0.031) but not OS (P = 0.061)." (PMID 28591216, 2017). "However, HSPD1 was also found to be upregulated and to act as an initiator of oxidative stress and neuroinflammation in diabetes, and HSPE1 stimulated mitochondrial stress and damaged the mitochondrial structure of chondrocytes." (PMID 38200905, 2024). "Additionally, there is growing evidence that Hspd1 modulates diabetes‐induced inflammation and protects against Aβ oligomer‐induced synaptic toxicity." (PMID 36642814, 2023). "Nevertheless, the finding suggested that HSPD1 may be a potential target gene to be interfered for a better prognosis of breast cancer, particularly for the breast cancer patients with diabetes." (PMID 28591216, 2017). "Diabetes and HSPD1 rs2605039 might also influence breast cancer survival." (PMID 28591216, 2017). "Diabetes and HSPD1 rs2605039 might also influence breast cancer prognosis." (PMID 28591216, 2017). "We also found that both diabetes and genetic variations of FTO, IL-6, HSPD1 genes were equally distributed across clinical characteristics of breast cancer." (PMID 28591216, 2017). "Similarly, in the retina, diabetes does not evoke the expected HSP response as total HSPB1 was unchanged, HSPD1/HSP60 was reduced in the mitochondria, HSPC/HSP90 was downregulated and only HSPA/HSP70 underwent upregulation." (PMID 29240668, 2017).
breast carcinoma (21 papers, 1996 to 2024). "GT/TT genotypes of HSPD1 rs2605039 was also associated with a better progression free survival for breast cancer patients [HR (95%CI): 0.70 (0.49, 0.99)]." (PMID 28591216, 2017). "It was revealed that T2DM individuals with CC genotype of IL-6 rs1800796 or GG genotype of HSPD1 rs2605039 were strongly associated with increased risk of breast cancer (OR (95%CI): 2.53 (1.45, 4.41) and OR (95%CI): 6.40 (2.29, 17.87), respectively) compared to non-T2DM individuals." (PMID 37510134, 2023). "Increased copy number of HSPD1 was associated with increased expression in stomach adenocarcinoma and breast cancer, while its up-regulation was observed in pancreatic adenocarcinoma regardless of whether HSPD1 gene was amplified or deleted." (PMID 34712697, 2021). "For example, B2M, CALML5, and HSPD1 are largely breast cancer–specific markers, but even these differ in their expression across the different three breast cancer PDXs." (PMID 36470535, 2023). "Large-scale GWAS of T2DM and breast cancer have provided evidence for shared susceptibility genes, including a fat mass and obesity-associated gene (FTO), the interleukin-6 (IL-6) gene, and heat-shock protein 60 encoded by HSPD1 gene." (PMID 37510134, 2023). "A better progression free survival for breast cancer patients was shown to be associated with GT/TT genotypes of HSPD1 rs2605039, suggesting HSPD1 influence on breast cancer survival." (PMID 37510134, 2023). "We further examined the correlation between circEIF3H and HSPD1/RBM8A/G3BP1 by qRT-PCT in 49 human breast cancer tissues and confirmed the positive correlation between circEIF3H and HSPD1/RBM8A/G3BP1 respectively." (PMID 35568705, 2022). "Heat shock proteins showed the most significant change of all the upregulated domains, with Hsp90AA1, Hsp90AB1, TRAP1, HspA5, HspB1, HspE1, HspD1, HspA1B, HspA8, HspA9, and HspA4 identified in breast cancer tissue." (PMID 31921692, 2019). "Multiple heat shock proteins, including Hsp90AA1, Hsp90AB1, TRAP1, HspA5, HspB1, HspE1, HspD1, HspA1B, HspA8, HspA9, and HspA4, were significantly upregulated in breast cancer tissue." (PMID 31921692, 2019). "Hsp90AA1, Hsp90AB1, TRAP1, HspA5, HspB1, HspE1, HspD1, HspA1B, HspA8, HspA9, and HspA4 were validated as potential biomarkers for breast cancer tissue." (PMID 31921692, 2019). "Genomic DNA samples extracted from blood samples of 1168 breast cancer cases of T2DM Chinese females were genotyped for three diabetes-related single nucleotide polymorphisms (SNPs) genetic factors FTO rs3751812, IL-6 rs1800796, and HSPD1 rs2605039." (PMID 37510134, 2023). "Taken together, these findings strongly suggested that HSPD1/RBM8A/G3BP1 could promote breast cancer progression and were correlated with poor prognosis." (PMID 35568705, 2022). "Furthermore, Kaplan–Meier survival analysis showed that breast cancer patients with high HSPD1, RBM8A, or G3BP1 expression respectively had significantly worse distant metastasis-free survival (DMFS) in the TCGA Cohort." (PMID 35568705, 2022). "HSPD1 was closely related to prognosis in both oral squamous cell carcinoma and breast cancer." (PMID 33232279, 2020). "Coming back to HSPE1, in a previous proteomic analysis this protein appeared with altered expression in MDA-MB-231 breast cancer cells (triple negative highly aggressive cells) and both HSPD1/HSPE1 have also been found upregulated in other cancer types associated with tumour cell transformation." (PMID 29954368, 2018). "All this data together suggest that not only the TRiC complex has a protagonist role in cancer behaviour but also that the HSPD1/HSPE1 complex is involved tightly with TRiC in proteostasis regulation, an association that is poorly understood in breast cancer and should be further studied." (PMID 29954368, 2018). "They conclude that HSPD1 could be one of the potential biomarkers for breast cancer progression and metastasis." (PMID 22357162, 2012).
breast carcinoma (continued). "Among women with CC genotype of IL-6 rs1800796 or GG genotype of HSPD1 rs2605039, diabetic individuals had a remarkably increased risk of breast cancer compared to non-diabetic women with ORs and 95%CIs of 2.53 (1.45, 4.41) and 6.40 (2.29, 17.87), respectively." (PMID 28591216, 2017). "An increased autoantibody level against HSPD1 has been reported in HCC and breast cancer and proposed as a marker for early detection." (PMID 33261560, 2020). "Accumulating evidence showed that HSPD1, RBM8A, and G3BP1 played a key role in tumor progression in several cancers; however, its effect on breast cancer proliferation and metastasis remains unclear." (PMID 35568705, 2022). "Notably, established protein biomarkers for metastatic breast cancer, such as EGFR, HSPD1, PRDX6, and TPM4, which are related to lymph node and regional metastasis, were also detected." (PMID 32489334, 2020). "In this context, we developed a new Myc-based Mito-Signature consisting of 3 mitochondrial genes (HSPD1; COX5B; TIMM44) for effectively predicting tumor recurrence (HR=4.69; p=2.4e-08) and distant metastasis (HR=4.94; p=2.8e-07), in ER(+) in breast cancer patients." (PMID 29080556, 2017).
Autoimmunity (13 papers, 2006 to 2024). The occurrence of an immune reaction against the organism's own cells or tissues. "Antibody responses to F-actin, RUVBL2, and HSPD1 have been also reported in various autoimmune conditions." (PMID 37751306, 2023). "Similarly, in a longitudinal pre- and post-therapy analysis, synovial HSPD1 expression was downmodulated selectively in patients with RA who had a good clinical response to rituximab, suggesting that the HSP60 autoimmunity might influence the clinical response to B cell–depleting therapy." (PMID 38950333, 2024).
colitis (12 papers, 2017 to 2026). Inflammation of the colon. "In B cells, there was upregulation of transcripts involved in protein synthesis and endoplasmic reticulum stress, such as Calr, Hspd1, Hspa5, in keeping with B cells adopting a secretory state in CPI-induced colitis." (PMID 37872166, 2023).
colorectal cancer (11 papers, 2011 to 2025). A primary or metastatic malignant neoplasm that affects the colon or rectum. "Clinically, data from the GEPIA 2 database indicated that higher expression levels of HSPD1 and HSP90 AA1 are associated with shorter overall survival in colorectal cancer patients." (PMID 40722058, 2025). "This broader relevance is supported by prior studies linking HSPD1 to breast, nonsmall cell lung, and colorectal cancers." (PMID 41370198, 2025). "HSPD1 has been recognized as a potential biomarker for tumor diagnosis and prognosis, especially in colorectal cancer." (PMID 32523426, 2020). "Genes such as PSME3 and HSPD1 were involved in the pathogenesis of many cancer types such as colorectal cancer and colon cancer, but these genes may be important for the growth of GBM." (PMID 31137733, 2019).
type 1 diabetes (11 papers, 2008 to 2025). "HSPD1 is involved in the two pathways Prion disease and Type I diabetes mellitus." (PMID 19284601, 2009). "This was also reflected in the KEGG pathway analysis of trans-mQTLs where type 1 diabetes was found to be an enriched pathway of relevance in human pancreatic islets, including the following genes: PTPRN2, HLA-DRB1, HLA-B, HLA-C, HSPD1 and HLA-DRB5 (Padj = 6.0×10−4)." (PMID 25375650, 2014).
hereditary spastic paraplegia (10 papers, 2014 to 2022). Hereditary spastic paraplegias (HSP) comprise a genetically and clinically heterogeneous group of neurodegenerative disorders characterized by progressive spasticity and hyperreflexia of the lower limbs. "Mutations of HSPD1 in hereditary spastic paraplegia and MitChap60 disease highlight possible implications for neurodegenerative disease." (PMID 25215595, 2014).
colon carcinoma (9 papers, 2017 to 2024). "Although HSPD1 was upregulated in all three adenocarcinomas, its association with reduced survival in colon cancer and better survival in lung cancer." (PMID 39542983, 2024). "We analyzed data from The Cancer Genome Atlas (TCGA) and found that the expression levels of HSPD1 mRNA were elevated in GBM, prostate cancer, colon cancer, and decreased in ccRCC." (PMID 31477750, 2019).
lung carcinoma (8 papers, 2021 to 2025). "Of these, Aco2, Idh2, Ndufs1, Hadh, Dlat, Itgam, Dlat, Hadha, Mrpl11, Dlst, and Hspd1 show potential as oncoproteins and tumor suppressors and warrant further study for their possible role in inflammation-driven lung cancer." (PMID 40429836, 2025). "Our results revealed HSPD1 as a ubiquitous lung cancer dependency gene, which maintains the metabolic fitness and promotes growth/survival, thus highlighting it as an attractive therapeutic target for NSCLC." (PMID 34364401, 2021). "In lung cancer, HSPD1 has been previously found highly expressed in NSCLC tissues and identified as a predictive marker for survival in both smokers and non-smokers patients." (PMID 34364401, 2021). "In conclusion, we showed that HSPD1 elimination interferes with NSCLC metabolic activity causing a strong OXPHOS-dependent energetic impairment, which the cancer cells fail to overcome, highlighting HSPD1 as a powerful theranostic marker for improving lung cancer therapy." (PMID 34364401, 2021). "Also, HSPD1 was proved to be highly expressed in lung cancer and displays worse patients' outcome." (PMID 35342421, 2022). "The sensitivity towards KHS101 is also independent from the lung cancer type or NSCLC histotype, suggesting that a HSPD1 targeting approach might be valuable also for other cancer types." (PMID 34364401, 2021).
leukodystrophy (7 papers, 2016 to 2022). Leukodystrophies are a group of rare, progressive, metabolic, genetic diseases that affect the brain, spinal cord and often the peripheral nerves. "Instead, mutations in HSPD1 are associated with hypomyelinating leukodystrophy as well as spastic paraplegia." (PMID 35328774, 2022). "The data is related to the research article entitled “Hypomyelinating leukodystrophy-associated missense mutation in HSPD1 blunts mitochondrial dynamics”." (PMID 26900593, 2016). "Two siblings, a younger brother with hypomyelinating leukodystrophy and an elder brother with severe intellectual disability and autistic features, had independent de novo variants of HSPD1 c.139T > G (p.Leu47Val) and HIP1 c.1393G > A (p.Glu465Lys), respectively." (PMID 30083362, 2018).